CD93 (CD93 molecule)
Diseases named in the same sentence as CD93 in open-access papers (continued):
Sharing a sentence is not in itself a finding about the gene and the disease.
glioma (continued). "Consequently, CD93 could be regarded as a practical marker for glioma-based evaluation of molecular pathological subforms and also of long-term survival." (PMID 36006582, 2022). "Similarly, MMRN2 was highly expressed in murine GL261 glioma vasculature, colocalizing with CD93." (PMID 29763414, 2018). "Moreover, there are few studies examining the immune properties of gliomas, particularly in the context of immunosuppressive processes, thus making it difficult for us to objectively recognize its role and deeply restricting the clinical translation of CD93-targeted therapies for glioma." (PMID 36006582, 2022). "Previous studies confirmed that CD93 formed granular membranes and involved in NEUT degradating, activating, as well as immune responses in glioma microenvironments." (PMID 36006582, 2022). "First, we plotted the Kaplan–Meier models using the survival statistics from glioma samples from the TCGA and CGGA sets, and those patients with highly expressed CD93 exhibited significantly shorter overall survival (OS) time (P < 0.0001)." (PMID 36006582, 2022). "Furthermore, the co-localization of CD93 and MMRN2 expression has been confirmed in the blood vessels of various human solid tumors, including melanoma, Ewing’s sarcoma, ovarian cancer, and glioma." (PMID 40943530, 2025). "Interestingly, CD93 deletion delayed tumor growth only in female mice with GL261 gliomas and T241 fibrosarcomas, but impaired glioma vasculature perfusion equally in both sexes." (PMID 40943530, 2025). "In regard to these roles and the biologic processes mediated by CD93 in the context of glioma, besides angiogenesis and ECM organization, we found that CD93 chiefly involved in leukocyte migrations, integrin-mediated signaling pathway, platelet degranulation and others." (PMID 36006582, 2022). "CD93 and MMRN2 expression correlates with increased fibronectin deposition in human glioma vessels." (PMID 29763414, 2018). "To determine whether CD93 is required for efficient β1 integrin activation and fibronectin fibrillogenesis during tumor angiogenesis, we analyzed tumor vessels in intracranial GL261 gliomas in WT and CD93–/– mice." (PMID 29763414, 2018). "Similar to our previous observation that CD93 expression is increased in the vasculature of human high-grade glioma (HGG), MMRN2 and fibronectin were significantly elevated in WHO grade III and IV glioma compared with low-grade glioma (LGG; WHO grade II) or control brain samples." (PMID 29763414, 2018). "CD93 markedly upregulated among HGG, MGMT promoter unmethylated subforms, IDH wild forms, 1p19q non-codeletion subforms, and mesenchyme type gliomas." (PMID 36006582, 2022). "Subsequent analyses of survival identified high-expression CD93 as a distinct prognostic variable for patients with gliomas, while earlier reports have displayed similar findings in the context of HGG, nasopharyngeal carcinoma and colon cancer but not in overall gliomas." (PMID 36006582, 2022).
melanoma (11 papers, 2011 to 2025). A malignant, usually aggressive tumor composed of atypical, neoplastic melanocytes. "CD93 deficiency in melanoma-bearing mice was associated with reduced endothelial barrier function in the primary tumor, enhanced expression of MMP9, and increased metastatic spread, which was reversed to wild-type levels when VEGFR2 signaling was inhibited." (PMID 38441970, 2024). "CD93 deficiency facilitates transendothelial migration of melanoma cells and promotes metastases." (PMID 38441970, 2024). "Next, we assessed whether the compromised endothelial barrier associated with CD93 deficiency can promote transendothelial migration of melanoma cells and formation of distant metastases." (PMID 38441970, 2024). "In a human pan-cancer analysis of transcriptomic and mutational data from several online databases, CD93 was found to be upregulated in most cancers such as cholangiocarcinoma, ovarian, pancreatic, gastric, melanoma, and kidney but down regulated in lung adenocarcinoma and bladder urothelial cancer." (PMID 38468017, 2024). "Altogether, these data show that CD93 deficiency impairs vascular integrity in melanoma." (PMID 38441970, 2024). "Finally, to assess whether tumor cell extravasation and seeding in lung tissue were facilitated by CD93 deficiency, melanoma cells were injected via the tail vein into the circulation of wild-type and CD93–/– mice." (PMID 38441970, 2024). "Therefore, we investigated whether CD93 deficiency affects endothelial junctions in the melanoma-associated vessels." (PMID 38441970, 2024). "In CD93 knockout (CD93−/−) mice, primary melanoma growth is inhibited, but metastasis increases due to disrupted adherens and tight junctions in tumor ECs and elevated matrix metalloproteinase 9 expression at metastatic sites." (PMID 40943530, 2025). "In line with the increased MMP9 expression around the tumor vasculature, a substantial reduction in the deposition of the ECM proteins fibronectin and collagen IV was observed in the perivascular region of HCmel12 melanomas in CD93–/– mice." (PMID 38441970, 2024). "Consistent with this, collagen IV and fibronectin were reduced in perivascular regions in primary melanomas and metastasis in CD93–/– mice." (PMID 38441970, 2024). "CD93 is required for maintaining tumor vessel integrity in murine melanoma." (PMID 38441970, 2024). "Similarly to the HCmel12 model, CD93 was highly expressed in the vasculature of B16F10 melanomas, and tumor growth was decreased in CD93–/– mice." (PMID 38441970, 2024). "Primary melanoma growth was hampered in CD93–/– mice, but metastatic dissemination was increased and associated with disruption of adherens and tight junctions in tumor endothelial cells and elevated expression of matrix metalloprotease 9 at the metastatic site." (PMID 38441970, 2024). "To investigate whether CD93 affects vascular integrity in metastatic tumors, we employed the murine HCmel12 melanoma model." (PMID 38441970, 2024). "Similarly, in the B16 melanoma mouse model, the inclusion of anti-CD93 improved the antitumor effect mediated by PD-1 and CTLA4 mAbs, as revealed by tumor growth and mouse survival curves." (PMID 36761750, 2023). "Moreover, a CD93-targeting monoclonal antibody (mAb) has been demonstrated to reduce tumor growth and enhance the effects of immunotherapy in pancreatic tumors or melanoma via the CD93/IGFBP7 pathway." (PMID 35812369, 2022). "Furthermore, CD93 blocking effectively elevated the proportion of effector T cells in melanoma, making tumors more sensitive to anti-PD-1/PD-L immune checkpoints treatment." (PMID 36006582, 2022). "CD93, MMRN2, and fibronectin expression was observed in the vasculature of primary lung cancer as well as in lung metastases and melanoma metastases." (PMID 38441970, 2024).
melanoma (continued). "We scored the fraction of blood vessels that expressed CD93 and its partners MMRN2 and fibronectin in tissue microarrays (TMAs) containing tumor tissue cores from primary and metastatic lung tumors as well as melanoma metastases." (PMID 38441970, 2024). "CD93 overexpression was found in tumor vasculatures, and it influenced the survival of patients in PDAC, PNET, melanoma, and colon cancer." (PMID 37483608, 2023). "Supporting that, CD93 overexpression was found in tumor vasculatures, and it influenced the survival of the host in PDAC, PNET, melanoma, and colon cancer." (PMID 35242761, 2022). "In B16 melanoma and KPC pancreatic cancer mouse models, the addition of an anti-CD93 antibody enhanced the anti-tumor effects mediated by immune checkpoint blockers, such as PD-1 and CTLA-4 monoclonal antibodies, inhibiting tumor growth and prolonging mouse survival." (PMID 40943530, 2025). "Moreover, novel interactions between tumor-secreted IGFBP-7 and CD93 on endothelial cells led to reduced angiogenesis and slowed tumor growth in in vitro models of melanoma, confirming the role of IGFBP-7:CD93 interactions in tumor development." (PMID 41226289, 2025). "Based on the TISIDB database, we observed CD93 expression differences between ICB therapy responders and ICB therapy non-responders of melanoma, urothelial cancer, and clear cell renal cell carcinoma." (PMID 36761750, 2023).
coronary artery disease (10 papers, 2012 to 2025). "CD93 plays an important role in efferocytosis since mutations in CD93 predispose patients to efferocytosis-associated diseases such as coronary heart disease, which is caused by the accumulation of apoptotic cells beneath the cardiac vasculature." (PMID 37443812, 2023). "The rs3746731 polymorphism of the CD93 gene was associated with a 1.26-times increased risk of developing coronary heart disease independently of cardiovascular risk factors such as hypertension, diabetes, and obesity." (PMID 37371490, 2023). "Soluble CD93 is associated with premature myocardial infarction, coronary artery disease, and other inflammatory conditions, with reduced levels of the soluble CD93 related to metabolic dysregulation." (PMID 33589722, 2021). "Interestingly, another study found that rs2749812 was associated with increased plasma sCD93 levels and increased CD93 mRNA expression in coronary artery disease." (PMID 37443812, 2023). "CD93 is reportedly associated with the risk of coronary artery disease." (PMID 28962592, 2017). "Numerous studies have identified a correlation between CD93 protein levels or gene polymorphisms and the prevalence of cardiovascular risk factors (e.g., hypertension, dyslipidemia, obesity) and diseases (e.g., heart failure, coronary artery disease, ischemic stroke)." (PMID 40943530, 2025). "Our aim is to review the available literature about the associations between sCD93 levels and CD93 genetic polymorphisms and the incidence of cardiovascular risk factors and CVD, such as heart failure, coronary artery disease, and ischemic stroke." (PMID 37371490, 2023). "It has been reported that soluble CD93 fragments are released during inflammation and their presence in the plasma of patients is a biomarker for coronary artery disease." (PMID 24809468, 2014). "Accumulating evidence suggests that CD93 may play a crucial role in various cardiovascular conditions, with differential expression observed across multiple CVDs, including diabetes, coronary heart disease, and atherosclerosis." (PMID 40943530, 2025). "Another mechanism by which CD93 may play a role in coronary artery disease is its role in endothelial homeostasis and microvasculature function." (PMID 37371490, 2023). "Moreover, elevated CD93 expression is also detected in the plasma of the patients who have overcome from coronary artery disease." (PMID 23272129, 2012). "Moreover, the plasma concentration of sCD93 has been proposed as a biomarker for conditions such as systemic sclerosis, allergic asthma, glucose metabolism regulation, and coronary artery disease (the specific role of CD93 in these diseases will be discussed in detail later)." (PMID 40943530, 2025). "Elevated soluble CD93 may be a biomarker for coronary artery disease." (PMID 23272129, 2012).
glioblastoma (8 papers, 2018 to 2025). The most malignant astrocytic tumor (WHO grade IV). "The latest research revealed that CD93 was also highly expressed in tumor-associated vasculature, including nasopharyngeal carcinoma, glioblastoma, colorectal cancer, and pancreatic ductal adenocarcinoma." (PMID 36761750, 2023). "Intriguingly, only CD93‐deficient female mice display aberrations in tumour growth and perfusion in orthotopic glioblastoma and fibrosarcoma models." (PMID 31287944, 2019). "In addition to changes in Mmps, we also found that glioblastoma was associated with an increased expression of mRNAs encoding microglial phagocytic receptors—Cd93, Msr1, Cd36, Olr1, Megf10, Clec7a, and Scarf1." (PMID 32299465, 2020). "We have previously shown that CD93 is involved in the regulation of endothelial barrier function and vessel maturation in an experimental model of glioblastoma." (PMID 38441970, 2024). "Supporting that is the fact that increasing evidence had shown that CD93 plays an important role in the angiogenesis and vasculature of cancer, including nasopharyngeal carcinoma, glioblastoma, colorectal cancer, and pancreatic ductal adenocarcinoma." (PMID 36761750, 2023). "Recent reports have confirmed that CD93 is overexpressed in glioblastoma (GBM) vasculature both in mRNA and protein level compared with low-grade gliomas (LGG) and normal brain tissue." (PMID 36006582, 2022). "Another study evaluated the role of CD93 in regulating glioblastoma angiogenesis." (PMID 37443812, 2023).
asthma (7 papers, 2019 to 2025). "We showed that CD93 is significantly associated with allergic inflammation using both in vitro and in vivo models, and the predictive power of CD93 for asthma diagnosis was modest." (PMID 31941986, 2020). "After adjusting for age and sex, a higher level of CD93 (≥138.5 μg/mL) was found to predict asthma with moderate sensitivity (71.4%) and specificity (82.4%) (AUC = 0.787, P < 0.001)." (PMID 31941986, 2020). "Previous studies have revealed that the serum CD93 level is significantly higher in patients with exacerbated asthma compared to those with stable asthma." (PMID 31941986, 2020). "We further assessed the usability of sCD93 for asthma diagnosis by a retrospective post-hoc analysis of the CD93 levels." (PMID 31941986, 2020). "Since the serum sCD93 level can be easily obtained and interpreted objectively, clarifying the potential role of serum CD93 in asthma patients would provide a valuable tool for clinical diagnosis and management." (PMID 31941986, 2020). "The serum CD93 level showed moderate predictive power (sensitivity, 71.4%; specificity, 82.4%) for asthma diagnosis in human subjects." (PMID 31941986, 2020). "Notably, both soluble and membrane-bound forms of CD93 are significantly elevated in several inflammatory conditions, such as asthma, peritonitis, and periodontitis." (PMID 40943530, 2025). "In addition, the outer domain of CD93 on the membrane surface can split or fall off easily under the stimulation of inflammation, forming soluble CD93 and promoting the process of asthma exacerbation." (PMID 35265666, 2021). "Importantly, the serum soluble CD93 level can be measured easily, which would be a benefit for patients and clinicians to detect asthma." (PMID 31941986, 2020). "Since CD93 can be detected in a soluble form in the serum, it can be easily and non-invasively measured, highlighting sCD93 as a useful surrogate to diagnose or assess asthma in practical clinical settings." (PMID 31941986, 2020). "HDM-induced asthma mice showed significant airway hyperresponsiveness and inflammation with Th2 cytokine activation, along with decreased CD93 expression in bronchial epithelial cells and lung homogenates but increased serum CD93 levels." (PMID 31941986, 2020). "In addition, this study suggests that CD93 has potential role to predict asthma in humans." (PMID 31941986, 2020). "With regards the unmet need for asthma biomarkers, we identified various mRNAs in the circulation that were uniquely expressed in the asthmatic subjects, including HIST1H3C, PRAM1, RAB6B and CD93." (PMID 31221987, 2019). "Because of small number of asthma subjects (n = 28), we could not find significant correlation of level of CD93 with lung function or level of eosinophil." (PMID 31941986, 2020). "Alfa-1-antitrypsin (SERPIN1A) and IL1RAP were elevated only in asthma patients with high LCI, as opposed to IgM, CD93 and CCL18 which were elevated also in asthma patients without small airway involvement." (PMID 35668386, 2022).
acute myeloid leukemia (6 papers, 2022 to 2025). Acute myeloid leukemia (AML) is a group of neoplasms arising from precursor cells committed to the myeloid cell-line differentiation. "Related research has also identified CD93 as a characteristic gene of leukemia stem cells (LSCs) associated with acute myeloid leukemia (AML) recurrence." (PMID 40943530, 2025). "CD93 chimeric antigen receptor T cells eliminate acute myeloid leukemia and spare hematopoietic stem and progenitor cells but exert on-target, off-tumor toxicity to endothelial cells." (PMID 36761750, 2023). "The application potential of iCAR technology was further corroborated by a similar approach to mitigate the on-target off-tumor toxicity of novel CD93-specific CAR T cells in acute myeloid leukemia (AML)." (PMID 36922828, 2023).
atherosclerosis (6 papers, 2015 to 2025). A disease characterized by the build-up of fatty material and calcium deposition in the arterial wall resulting in partial or complete occlusion of the arterial lumen. "The expression of CD93 in monocytes and macrophages was associated with atherosclerosis in both animal and human studies." (PMID 37371490, 2023). "Recently, CD93 in MΦ was linked to atherosclerosis development." (PMID 35166040, 2022). "The essential physiological functions of CD93 are integral to the initiation and advancement of atherosclerosis." (PMID 40943530, 2025). "Our best candidate genes, Hdc, Mertk and Cd93 for Aath4 and Stab2 for Aath5, all play pivotal roles in early processes of atherosclerosis by regulating leukocyte recruitment, macrophage activation, and inflammation." (PMID 25689165, 2015). "Together, these studies underscore the strong link between CD93 expression and atherosclerosis." (PMID 40943530, 2025). "Accordingly, because the study was retrospective, we cannot measure the more specific markers for understanding immune function and atherosclerosis development, like VCAM-1 or CD93." (PMID 39797206, 2024). "Since atherosclerosis represents the hallmark sign of CVD and CD93 has been shown to regulate several processes that, if impaired, may induce the initiation or progression of the atheroma, it appears evident why CD93 has gained increasing interest in cardiovascular research." (PMID 37371490, 2023). "Considering that both CD93 and sICAM-1 are known promoters of atherosclerosis, it is not surprising that these inflammatory markers would additionally compound existing CVDs." (PMID 38999835, 2024).
Hypertension (6 papers, 2021 to 2025). The presence of chronic increased pressure in the systemic arterial system. "The study by Sharma and colleagues found that two intergenic single nucleotide polymorphisms (SNPs) that regulate both thrombomodulin and CD93 levels, and CD93 SNPs rs7492 and rs2749812, were associated with hypertension at high altitude." (PMID 37371490, 2023). "Moreover, SNPs rs7492 and rs2749812 of CD93 were associated with hypertension in high-altitude areas." (PMID 40943530, 2025). "Finally, a study on the associations between genetic variants of Thrombospondin-1 Levels and high-altitude hypertension found significant associations between CD93 polymorphisms and arterial hypertension in a study sub-group of 349 people living at high altitude (>3500 mt)." (PMID 37371490, 2023). "The SNPs with the highest risk towards hypertension were intergenic SNPs rs1006472 of CD8B2;ST6GAL2, and rs1998081 and rs2424515 of THBD;CD93." (PMID 34575042, 2021). "This is supported by studies on vascular and endothelial dysfunction markers, such as CD93 and VCAM-1, which have been associated with both nephropathy and cardiopathy—further reinforcing the broader implications of vascular anomalies in hypertension development." (PMID 40004797, 2025). "VEGF inhibitors in tumor therapy often cause hypertension and nephrotoxicity 33, 34, which probably will not or less occur with M057 therapy, as CD93 is downstream of VEGF signaling." (PMID 38250037, 2024). "The search terms included: cardiovascular, heart failure, acute stroke, myocardial infarction, stroke, peripheral artery disease, cardiovascular death, MACE, hypertension, metabolic syndrome, hyperuricemia, diabetes, cd93, c1qr, C1qR1, complement protein 1 q subcomponent receptor." (PMID 37371490, 2023).